TNF (tumor necrosis factor)
Diseases named in the same sentence as TNF in open-access papers (continued):
Sharing a sentence is not in itself a finding about the gene and the disease.
visceral leishmaniasis (34 papers, 2008 to 2025). A severe form of leishmaniasis characterized by irregular bouts of fever, substantial weight loss, swelling of the spleen and liver, and anemia (which may be serious). "Visceral leishmaniasis (VL) is associated with increased circulating levels of multiple pro-inflammatory cytokines and chemokines, including IL-12, IFNγ, and TNFα, and elevated expression of IFNγ mRNA in lesional tissue such as the spleen and bone marrow." (PMID 25275531, 2014). "Previous reports have shown that in vivo, pro-inflammatory cytokines such as IL-1β, IL-6 and TNF-α, as well as chemokines, are induced in the initial events of L. major and L. donovani, causative agents of cutaneous and visceral leishmaniasis infection in the Old World, respectively." (PMID 23497381, 2013). "In the context of L. infantum-induced visceral leishmaniasis, we assessed immune mediators including TNF, IL-1β, CXCL10, IL-12p70, IL-18, IL-23, and C-C motif chemokine ligand 2 (CCL2)." (PMID 40794782, 2025). "We employed ROC curve analysis to thoroughly assess the potential of IL-1β, IL-6, IL-8, IL-10, IL-12, and TNF-α as predictive biomarkers for identifying fatal cases of kala-azar." (PMID 41003560, 2025). "It has also been demonstrated that TNF-α is elevated in the serum of individuals with active visceral leishmaniasis (VL), often in conjunction with high levels of IFN-γ." (PMID 38455048, 2024). "Leish-111f induces increased CD4+ cells that produce IFN-γ, IL-2, and TNF-α, which confers desirable protection against visceral leishmaniasis with significant reductions in parasite loads." (PMID 35812381, 2022). "Visceral leishmaniasis occurring in the setting of TNF-α administration has been recognized in case reports from Europe since at least 2004." (PMID 33799892, 2021). "When the disease is already established, however, increased levels of the proinflammatory cytokines IFN-γ, tumour necrosis factor-α (TNF-α), IL-6, and IL-8 can be found in visceral leishmaniasis (VL) patients' sera." (PMID 29230410, 2017). "Animals with sub-clinical infection expressed more IFN-γ and TNF-α than those with visceral leishmaniasis; in the same study, it was shown that animals with clinical manifestations had more parasites in the lymph node than those with asymptomatic infection." (PMID 24146743, 2013). "Increased levels of TNF have been observed in human and murine experimental models of visceral leishmaniasis." (PMID 22242159, 2012). "Concentrations of IL-1β and TNF-α are often elevated in individuals with symptomatic kala-azar." (PMID 41003560, 2025). "Although the finding of higher pre-treatment IL-1β, IL-12, and TNF-α levels in survivors suggests they serve as protective biomarkers in individuals with kala-azar, the accuracy was not sufficient for adequate diagnostic utility." (PMID 41003560, 2025). "Among 49 TNF-alpha inhibitor recipients with cutaneous, mucosal, and visceral leishmaniasis (predominately cutaneous) in the Mediterranean region; relapse was uncommon (5 out of 49 patients), but it was associated with a failure to discontinue the patient’s immunosuppressive agent." (PMID 33799892, 2021). "In the present study we investigated whether combination of IFN-γ and TNF-α has better therapeutic strength than individually using one of these cytokines in Visceral Leishmaniasis (VL) patients." (PMID 29953494, 2018). "Thus, our results for TNF- α and IL-4 are in accordance with the literature regarding their role in canine visceral leishmaniasis." (PMID 23668673, 2013). "Hence, we cannot exclude the possibility that periods of high TNF production take place during the natural course of canine visceral leishmaniasis." (PMID 22242159, 2012). "In Sudan, individuals with kala-azar have high levels of IFN-γ, TNF-α, IL-4, IL-6, IL-10, IL-12, and IL-17A." (PMID 41003560, 2025).
visceral leishmaniasis (continued). "In this context, pretreatment serum levels of interferon-gamma (IFN-γ), tumor necrosis factor-α (TNF-α), IL-4, IL-6, IL-8, IL-10, and IL-27 are elevated in Brazilian individuals with untreated kala-azar." (PMID 41003560, 2025). "Therapy with AmB induced elevated production of TNFα, IFNγ and IL-12 in splenocytes of treated mice, and PBMC of kala-azar patients with reduced IL-4, IL-10 and TGFβ production." (PMID 25884796, 2015). "Consistent with that theory, in experimental models of visceral leishmaniasis, it has been reported that the blockade of PD-1 reduces the parasite burden, restores the T cell proliferation capacity and increases the production of IFN-γ and TNF-α." (PMID 30510917, 2018). "Contrary to commonly held views, in the setting of experimental visceral leishmaniasis neither IFNγ nor TNF signalling in HSCs was required for their functional exhaustion." (PMID 28671989, 2017). "In addition, in patients cured from visceral leishmaniasis, proliferation in response to NH36 and F1 was accompanied by a significant increase of IFN-γ and TNF-α secretion, which was 42–43% higher, in response to F1 than to NH36." (PMID 28747911, 2017). "Elevated levels of IL-1β, IL-12, and TNF-α may have a protective effect in individuals with kala-azar; however, in the present study, these cytokines did not demonstrate adequate diagnostic utility." (PMID 41003560, 2025). "In addition, infection control in visceral leishmaniasis has been related to a Th1-type immune response, in which the pro-inflammatory cytokines IFN-γ/TNF must overcome the effects of the regulatory cytokine (IL-10), while susceptibility is related to a deficient pro-inflammatory response." (PMID 39771984, 2024).
bronchiectasis (33 papers, 2007 to 2025). Segmental, irreversible dilation of the bronchial tree resulting in the accumulation of secretions which leads to obstruction. "An increased risk of bacterial and fungal infection in patients with fPS is associated with both immunosuppressive or anti-TNF-α treatment and structural lung abnormalities such as bronchiectasis or fibrocystic areas." (PMID 40217830, 2025). "Bronchiectasis is associated with elevated levels of pro-inflammatory cytokines and chemokines such as IL-8, IL-6 and tumour necrosis factor-α (TNF-α) in bronchoalveolar lavage fluid (BALF)." (PMID 40174958, 2025). "Risk factors for exacerbations were the presence of bronchiectasis on a chest CT scan and anti-TNFα treatment, reflecting more severe lung disease or increased immunosuppression." (PMID 40217830, 2025). "Previous studies have also demonstrated associations of TNF-α and IL-8 levels with computed tomography severity scores in adults with bronchiectasis." (PMID 33886789, 2021). "Risk factors for exacerbations include underlying bronchiectasis, longer disease duration, African American race, previous steroid treatment, and anti-tumor necrosis factor (TNF) therapy." (PMID 29861437, 2018). "Airway inflammation in bronchiectasis is characterised by neutrophil-dominated inflammation associated with elevated levels of proinflammatory cytokines and chemokines such as IL-8, IL-6 and TNF-α in bronchoalveolar lavage fluid (BALF)." (PMID 25822228, 2015). "One may also evoke, in PID-related bronchiectasis as in other causes of bronchiectasis, many other predisposing factors supposed to be involved in airways inflammation such as mannose-binding lectin gene polymorphism or high serum concentration of TNF alpha." (PMID 31801528, 2019). "Proinflammatory cytokines, such as TNF-α, IL-6, IL-8, and IL-1b, were studied, as they have been found elevated in sputum or bronchoalveolar damage in bronchiectasis patients." (PMID 32823681, 2020). "Previous studies have found that systemic inflammatory markers such as C reactive protein and airway cytokines (tumor necrosis factor-α, IL-1, IL-8) are increased in patients with bronchiectasis." (PMID 30717716, 2019). "Both CD8+ T cells and NKT that express pro-inflammatory IFN-γ and TNF-α have been described in paediatric bronchiectasis." (PMID 29788954, 2018). "The BAL fluid levels of the cytokines (IL-8, IL-1β, IL-6, TNF-α, IL-12) were found to be significantly elevated in patients of bronchiectasis when compared with controls (p < 0.0001)." (PMID 17224076, 2007). "Significantly elevated levels of proinflammatory IL-6, TNF-α, and IL-12 were likewise noted in cases with bronchiectasis versus healthy controls." (PMID 17224076, 2007). "In patients with bronchiectasis, TNF-α in bronchial secretions has been shown to enhance the expression of intercellular cell adhesion molecule-1 in bronchial epithelial cells, which may contribute to sustained neutrophil recruitment to the airways." (PMID 40174958, 2025). "A small study in children with bronchiectasis has shown elevated systemic proinflammatory lymphocytes (TNF-a, IFN-y, perforin, and granzyme), however, more studies are needed to identify sensitive and non-invasive markers of low-level inflammation (both airway and systemic) in children." (PMID 36186641, 2022). "A previous analysis of 385 patients with bronchiectasis showed that bacterial density was directly correlated with airway and systemic inflammatory markers, such as myeloperoxidase activity, neutrophil elastase activity, and tumor necrosis factor-α levels." (PMID 33573691, 2021). "However, another study showed increased levels of TNF-α in adults with severe bronchiectasis when comparison to the controls." (PMID 33886789, 2021).
bronchiectasis (continued). "The current data demonstrate highly significant increases in all Th17 pathway-associated chemokines and cytokines measured in the airways of adult bronchiectasis subjects, including pathway effectors (IL-17A, IL-6, IL-8 and TNF-α) and regulators (IL-1α, IL-1β, IL-6 and IL-23)." (PMID 25822228, 2015). "In this study, the positive correlation between the TNF-α levels in BAL fluid and the HRCT scores in patients with bronchiectasis caused by mustard gas inhalation may approve this hypothesis." (PMID 17224076, 2007). "Therefore, we aimed to evaluate acute systemic levels of proinflammatory cytokines (IL-17a, IL-1β, IL-8, and tumor necrosis factor alpha (TNF-α)) and high-sensitivity C-reactive protein (hsCRP) during bronchiectasis exacerbations and follow-up (days 30 and 60)." (PMID 32823681, 2020). "Common pro-inflammatory markers such as TNF-α, IL-8, NE and matrix metalloproteinases − 2, − 8 and − 9 (MMP2, MMP8 and MMP9), are all elevated in bronchiectasis with the latter two indicative of a poorer prognostic outcome." (PMID 29788954, 2018). "There is also increased production of inflammatory cytokines tumor necrosis factor alpha (TNF-α) and IL-1β and adhesion molecules such as E-selectin in the airways of patients with bronchiectasis." (PMID 29744361, 2018). "There were significant differences in cytokine (IL-8, IL-1β, IL-6, TNF-α, IL-12) levels of BAL fluid between patients with bronchiectasis and healthy controls." (PMID 17224076, 2007). "Another study pointed out the high concentration of TNF-a in the plasma of patients with non-CF bronchiectasis, indicating the high accumulation of serum neutrophils." (PMID 41149860, 2025). "While hs-CRP has been assessed in this study for its role in predicting bronchiectasis exacerbation, other inflammatory markers such as plasma IL-1β, IL-8, TNF-α, and LTB4 were not examined as they were not routinely available in our centre." (PMID 38350918, 2024). "In a previous study, the serum levels of IL-8 in adults with bronchiectasis were not significantly different from those in the control group, and TNF-α was not detectable in either group." (PMID 33886789, 2021). "The most comprehensive BALF study in adult non-CF bronchiectasis demonstrated increased levels of neutrophil elastase, myeloperoxidase, TNF-α, IL-6 and IL-8 but not IL1β compared to controls." (PMID 25822228, 2015). "Similarly, the most severe form of bronchiectasis is followed by a more intense inflammatory process, represented, for instance, by increased levels of TNF-α in a colonized group compared with a noncolonized group." (PMID 33886789, 2021). "Bacterial load in non-CF bronchiectasis has been correlated with increases in airway (NE, IL-8, IL-1β and TNF-α) and systemic (ICAM-1, E-selectin) derived inflammatory markers, phenomena confirmed in vitro using bronchial epithelial cell lines treated with sputum from bronchiectasis patients." (PMID 29788954, 2018). "Compared to normal controls, subjects with non-CF bronchiectasis also had highly significantly elevated BALF levels of all measured Th17 pathway cytokines (IL-1α, IL1β, IL-6, IL-8, IL-23 and TNF-α (p<0.0001 for all)." (PMID 25822228, 2015).
chronic lymphocytic leukemia (33 papers, 1998 to 2026). "In non-Hodgkin’s lymphoma, acute and chronic myeloblastic leukemia and chronic lymphocytic leukemia high levels of TNF-α and its receptors are associated with poor outcome and therapy resistance." (PMID 37610672, 2023). "Previous study indicated that knockdown of LEF1 resulted in TNF-α induced necroptosis in chronic lymphocytic leukemia cells." (PMID 36101745, 2022). "Liu reported that LEF1 is a key regulator of the necroptotic machinery, and knocking it down sensitized chronic lymphocytic leukemia cells to TNFα/zVAD-induced necroptosis." (PMID 36389690, 2022). "CX3CR1, a TNF target found to be down-regulated by SB225002 treatment, has been implicated in chronic lymphocytic leukemia attraction and adhesion to bone marrow stromal cells." (PMID 26302043, 2015). "Similarly, the low levels of RIPK3 and CYLD expression developed chronic lymphocytic leukemia (CLL) cells to resistance from TNF-α/zVAD-induced necroptosis." (PMID 36361505, 2022). "Higher levels of TNF-α have been observed in B-cell chronic lymphocytic leukemia (CLL)." (PMID 33986746, 2021). "Tumor necrosis factor (TRAF4), which is connected to CD40 activation and B-cell receptor signaling, is affected by miR-29, which is observed in chronic lymphocytic leukemia (CLL)." (PMID 41614928, 2026). "Similar observations were made in chronic lymphocytic leukemia (CLL) patients, in which the total number of ILC1s was increased, while the percentage of TNF-α-producing ILC1s was decreased." (PMID 35962192, 2022). "The first case was a 77-year-old immunosuppressed individual with B cell chronic lymphocytic leukemia who exhibited increased levels of the cytokines, interleukin (IL)1β, 6, 8, 10, interferon gamma (IFN)-γ and tumor necrosis factor (TNF)-α." (PMID 35430702, 2022). "The activity of chronic lymphocytic leukemia cells can be reversed by wogonin-mediated TNF-α via the transfer of T-cell leukemia cells and inhibits TNF-α-induced NF-kB pathway activity." (PMID 36686745, 2022). "CXCL13 and CCL19 together can inhibit the TNFα-mediated apoptosis of the CD23+ CD5+ B cell lineage, which is the commonest malignant cell type in acute and chronic lymphocytic leukemia." (PMID 30819249, 2019). "In a mouse model of chronic lymphocytic leukemia, targeting MΦs using an anti-CSF1R mAb efficiently inhibited disease progression; interestingly, the leukemic cell death was dependent on TNF-α signaling and tumor microenvironment reprogramming toward an antitumoral phenotype." (PMID 34771453, 2021). "In an in vitro chronic lymphocytic leukemia (CLL) study, culture with blinatumomab significantly increased the levels of IFN-γ, TNF-α, TNF-β and IL-8 (interleukin-8)." (PMID 37610672, 2023).
food allergy (33 papers, 2010 to 2025). Gastrointestinal disturbances, skin eruptions, or shock due to allergic reactions to allergens in food. "Furthermore, we also determined the changes in TNF-α, a pro-inflammatory cytokine, reflecting the strength of the inflammatory response caused by food allergy." (PMID 36832810, 2023). "There is no filaggrin in the intestinal mucosa, but studies described a change in the tight junctions due to higher TNF‐α concentration present in patients with food allergies." (PMID 40386328, 2025). "A previous study demonstrated that HMO treatment elevated the production of IL-10 and decreased the production of TNF-α in mouse mast cells, thereby alleviating the symptoms of food allergy." (PMID 37372011, 2023). "In the study of human umbilical cord-derived MSCs in the food allergy model, allergic symptoms and IL-4, TNF-α mRNA levels, inflammatory cells, and goblet cells in the colon were decreased by MSCs and MSC-CM." (PMID 35203718, 2022). "S100A8/A9 and inflammatory-related factors, including TLR4, NF-κB, TNF-α, IL-6 and IL-1β, is closely related to food allergies." (PMID 33499808, 2021). "The study measured TNF-α concentrations in peripheral blood mononuclear cells of each patient group and found that patients with gastrointestinal food allergies had significantly greater TNF-α concentrations than those seen in other groups." (PMID 33072241, 2020). "Conversely, studies in humans and mice with food allergy have demonstrated increased IL-4 and TNF-alpha and decreased IL-10 concentrations." (PMID 31164117, 2019). "An increase in the pro-inflammatory cytokine TNF-alpha has been shown in cow-milk allergy in children and experimental food allergy in mice." (PMID 31164117, 2019). "The present data showed that the high levels of specific IgE, IL-4 and TNF-α in the IBD patients with food allergy were down regulated after the therapy of SIT and CB, while the levels of antigen-specific IgG4 were up regulated." (PMID 27499766, 2016). "Among the mediators of food allergy, various cytokines have been described such as tumor necrosis factor (TNF-α), IL-1, IL-4, IL-5, IL-6, and IL-13." (PMID 23730302, 2013). "Our results indicate that epigenetic regulation may interact with immune communication pathways, including TNF/NF-κB, in food allergy development." (PMID 41153772, 2025). "Pathophysiology of non-IgE-mediated food allergy is poorly understood, though IL-2, IL-4, IL-5, IL-13, IL-17, tumor necrosis factor (TNF)-α, and TGF-β are thought to be associated." (PMID 35203718, 2022). "Unlike the gut microbiota dysbiosis–food sensitization model, this increase in inflammatory levels, including TNF-α and blood immune cells, may be responsible for the aggravation of food allergies." (PMID 34684316, 2021). "Gut microbiota dysbiosis participates in the immune response of food allergies and promotes the occurrence of TNF-α-mediated systemic inflammation, which may be related to an increased susceptibility to food allergies." (PMID 34684316, 2021). "We have also previously reported that the non-T cell fraction from food allergic infants showed increased inflammatory cytokine responses (TNFα, IL-6, IL-1β, and IL-8) to LPS stimulation, and that this was more pronounced in infants with persistent food allergy outcomes." (PMID 33072108, 2020). "We also observed high levels TNF-α in the colon mucosa, which further corroborates the results that food allergy is associated with the pathogenesis of IBD; TNF-α is a critical inflammatory factor in IBD because administration of anti-TNF-α can well alleviate the clinical symptoms of IBD16." (PMID 27604348, 2016). "Although increased production of IgE and Th2 cytokines (IL-4, IL-5 and IL-13) are considered common markers of food allergy, absence of IgE or increased levels of Th1 cytokines (IL-2, IFN-γ and TNF-α) have also been observed in several instances of food allergy, mainly in response to cow's milk." (PMID 21211037, 2011).